ADGRV1 (adhesion G protein-coupled receptor V1)
Description:
G protein-coupled receptor which has an essential role in the development of hearing and vision. Couples to G-alpha(i)-proteins, GNAI1/2/3, G-alpha(q)-proteins, GNAQ, as well as G-alpha(s)-proteins, GNAS, inhibiting adenylate cyclase (AC) activity and cAMP production. Required for the hair bundle ankle formation, which connects growing stereocilia in developing cochlear hair cells of the inner ear. In response to extracellular calcium, activates kinases PKA and PKC to regulate myelination by inhibiting the ubiquitination of MAG, thus enhancing the stability of this protein in myelin-forming cells of the auditory pathway. In retina photoreceptors, the USH2 complex is required for the maintenance of periciliary membrane complex that seems to play a role in regulating intracellular protein transport. Involved in the regulation of bone metabolism. [ADGRV1 subunit beta]: Cleaved ADGRV1 beta-subunit couples with G-alpha(i)-proteins, GNAI1/2/3, and constitutively inhibits adenylate cyclase (AC) activity with a stronger effect than full ADGRV1.
Synonyms: GPR98; KIAA0686; MASS1; VLGR1; DKFZp761P0710; FEB4; USH2B; USH2C; VLGR1b
Tractability: Antibody: UniProt places it where antibodies can reach, with medium confidence; UniProt predicts a signal peptide or a membrane-spanning region; its Gene Ontology location is reachable by antibodies, with medium confidence.
Safety:
Unwanted effects reported when the protein is acted on. In parentheses: how it was acted on, where the effect was seen, and who reports it.
opioid dependence (source: ClinPGx)
Gene: Protein-coding gene on chromosome 5 (90,529,344 to 91,164,437, forward strand). Ensembl gene ENSG00000164199.
Subcellular location: Cell membrane; Cell projection, stereocilium membrane; Photoreceptor inner segment
Subcellular location (Human Protein Atlas): Vesicles; Basal body
Pathways (Reactome):
Developmental Biology: EGR2 and SOX10-mediated initiation of Schwann cell myelination
Gene Ontology:
Molecular function: calcium ion binding; protein binding; adenylate cyclase inhibitor activity; G protein-coupled receptor activity; G-protein alpha-subunit binding; transmembrane signaling receptor activity
Biological process: maintenance of animal organ identity; nervous system process; photoreceptor cell maintenance; sensory perception of light stimulus; sensory perception of sound; cell-cell adhesion; cellular response to calcium ion; detection of mechanical stimulus involved in sensory perception of sound; establishment of protein localization; G protein-coupled receptor signaling pathway; inner ear development; inner ear receptor cell differentiation; inner ear receptor cell stereocilium organization; nervous system development; positive regulation of bone mineralization; regulation of protein stability; self proteolysis; visual perception; animal organ development; cell communication; cell surface receptor signaling pathway; regulation of developmental process
Cellular component: cell surface; cytoplasm; extracellular exosome; receptor complex; membrane; periciliary membrane compartment; photoreceptor inner segment; plasma membrane; stereocilia ankle link; stereocilia ankle link complex; stereocilium; USH2 complex; protein-containing complex; stereocilium membrane
Genetic constraint (gnomAD): Loss-of-function variants: 228 observed, 399.57 expected, observed/expected ratio (o/e) 0.57, 90% interval 0.51 to 0.64. The upper end of that interval is the gene's LOEUF score, 0.64, which puts it in group 2 of 6, group 1 being the genes least tolerant of losing a copy. Missense variants: 5,660 observed, 6,159.8 expected, observed/expected ratio (o/e) 0.92, 90% interval 0.9 to 0.94. Synonymous variants: 2,131 observed, 2,223.7 expected, observed/expected ratio (o/e) 0.96, 90% interval 0.92 to 0.99.
Gene-disease validity (ClinGen):
ClinGen rates the evidence that ADGRV1 causes each of these diseases.
Usher syndrome type 2 (autosomal recessive): Definitive. A syndrome characterized by congenital, bilateral sensorineural hearing loss that is mild to moderate in the low frequencies and severe to profound in the higher frequencies, no abnormalities in the vestibular system, and retinitis pigmentosa.
nonsyndromic genetic hearing loss (autosomal recessive): Disputed. A disease characterized by hearing loss that is not part of a larger syndrome.
Homologues: Orthologues: chimpanzee ADGRV1 (99% identical), macaque ADGRV1 (97% identical), dog ADGRV1 (88% identical), pig ADGRV1 (86% identical), rabbit ADGRV1 (83% identical), mouse Adgrv1 (80% identical), rat Adgrv1 (80% identical), zebrafish adgrv1 (52% identical), tropical clawed frog adgrv1 (29% identical). Paralogues in human: FREM2 (8% identical), FRAS1 (6% identical), SLC8A1 (5% identical), FREM3 (5% identical), FREM1 (5% identical), SLC8A2 (5% identical), SLC8A3 (4% identical).
Diseases named in the same sentence as ADGRV1 in open-access papers:
ADGRV1 is named in the same sentence as 89 diseases in open-access papers, as found by Europe PMC text mining. Sharing a sentence is not in itself a finding about the gene and the disease. The quoted sentences say what the papers report.
Usher syndrome (55 papers, 2011 to 2026). A syndromic diseae characterized by the association of sensorineural deafness (usually congenital) with retinitis pigmentosa and progressive vision loss. "Mutations in ADGRV1 were linked not only to Usher syndrome (USH), which causes deaf-blindness, but recently, also to epilepsy." (PMID 42002803, 2026). "WES analysis identified two compound heterozygous variants within the ADGRV1 (NM_032119.4) gene, known to be associated with Usher syndrome, type 2C (MIM: #605472)." (PMID 41007806, 2025). "Adhesion G protein-coupled receptor V1 (ADGRV1) plays a crucial role in hair cell development, and ADGRV1 mutations are associated with Usher syndrome (USH) 65-67." (PMID 40860157, 2025). "Another patient (P49) with Usher syndrome was found to carry LP variants in the ADGRV1 gene, in addition to two LP/VUS variants in the MYO15A gene." (PMID 41000418, 2025). "Pathogenic variants in the ADGRV1 gene, previously named MASS1, VLGR1 or GPR98, have been identified as the underlying cause for Usher syndrome type 2C (USH2C)." (PMID 37371069, 2023). "Both USH1G and ADGRV1 are linked to Usher Syndrome (annotated as # 606943 and # 605472, respectively, in the OMIM database), a rare autosomal recessive disorder characterized by profound congenital hearing impairment and subsequent retinitis pigmentosa." (PMID 37893031, 2023). "As a consequence of mutations in the ADGRV1 gene, patients with Usher syndrome type 2C present with congenital hearing impairment and a progressive loss of vision due to RP." (PMID 37371069, 2023). "ADGRV1 is one of the biallelic pathogenic identification markers of Usher syndrome, which is characterized by congenital bilateral sensorineural hearing loss." (PMID 35735060, 2022). "ADGRV1 variants are a rare cause of Usher syndrome, which is reflected by the scarcity of related phenotypic reports." (PMID 34638692, 2021). "Some PSGs that form hair bundle links are also implicated in vision; for example, PCDH15, USH2A, and ADGRV1 are all involved in Usher syndrome, congenital deafness due to stereocilia disorganization with associated progressive retinitis pigmentosa." (PMID 34137817, 2021). "The remaining three solved cases suffered from Usher syndrome due to putative pathogenic variants in ADGRV1, CDH23 and USH2A, one family for each gene." (PMID 33297549, 2020). "Mutations in ADGRV1 often cause the following two disorders: epilepsy and Usher syndrome type 2C.148, 149, 150 The occurrence of epilepsy may be associated with defective cell migration caused by ADGRV1 dysfunction." (PMID 39935605, 2025). "Variants of the ADGRV1 gene cause Usher syndrome type 2C (USH2C)." (PMID 40443611, 2025). "Even so, significant differences were found in the genetic architecture of Usher syndrome for the present cohort, as illustrated by the comparatively high prevalence of ADGRV1 variants, present in 14.5% of families, but found to be less common in Spanish or North American cohorts." (PMID 38189974, 2024). "Interestingly, he had albinotic fundus without any evidence of retinitis pigmentosa in spite of carrying a known variant in ADGRV1 causing Usher syndrome type 2 C." (PMID 34276053, 2021). "In cochlear hair cells, AC6 distribution relies on an adhesion GPCR, ADGRV1, which is associated with Usher syndrome (USH), a condition of combined hearing and vision loss." (PMID 37127773, 2023). "Mutations in VLGR1/ADGRV1 cause human Usher syndrome (USH), a form of hereditary deaf-blindness, and have been additionally linked to epilepsy." (PMID 35630584, 2022). "For example, two patients carried biallelic variants within the ADGRV1 and USH2A genes, both associated with Usher syndrome." (PMID 41007806, 2025). "Whilst suitable for a number of ciliopathy-related genes, such as RPGR (3.5 kb), many genes are beyond this capacity, including CEP290 (7.4 kb) and several of the Usher-syndrome-associated genes (MYO7A: 6.6 kb, CDH23: 10 kb, ADGRV1: 18.9 kb, USH2A: 15.6 kb)." (PMID 38474133, 2024).
Usher syndrome (continued). "Our investigation revealed in both the proband and her sister a very rare truncating variant in USH1G and a previously undescribed missense substitution in ADGRV1, two genes linked to type I (OMIM 606943) and type II (OMIM 605472) Usher syndrome, respectively." (PMID 37893031, 2023). "Mutations of the ADGRV1 (VLGR1) gene in humans are associated with the development of myoclonic epilepsy and Usher syndrome." (PMID 36428502, 2022). "Most of the syndromic diagnoses masquerading as NSHL were related to Usher syndrome (eight patients with causative mutations in the USH2A gene, three in the MYO7A gene, and one in the ADGRV1 gene)." (PMID 36555390, 2022). "Usher syndrome, most frequently due to biallelic variants in MYO7A (USH1B in 16 probands), USH2A (17 probands), and ADGRV1 (USH2C in 7 probands), was diagnosed in 44 of 59 (75%) unrelated probands." (PMID 34148116, 2022). "Using a multi-omic approach, we identified three novel pathogenic variants in two Usher syndrome genes (USH2A and ADGRV1) in cases initially referred for isolated vision or hearing loss." (PMID 31046701, 2019). "In a recent meta-analysis including all of the known genes causing usher syndrome, USH2A (50%) mutations are the most common with ADGRV1 mutations being less frequent (5%) in patients with both visual and hearing impairments." (PMID 31046701, 2019). "Examples are ADGRG1 (GPR56) and ADGRV1 (VLGR1), where gene mutations cause brain malformation (bilateral frontoparietal polymicrogyria) and a form of Usher syndrome, respectively." (PMID 27516204, 2016). "This confirms the role of the ADGRV1 mutant in the pathogenesis of Usher syndrome type 2C." (PMID 39935605, 2025). "Mutations in ADGRV1 and CIB2 have been linked to three separate subtypes of Usher syndrome." (PMID 39060957, 2024). "The majority of the studies involving Usher syndrome patients with ADGRV1 variants included ≤ 5 cases with no or minimal phenotypic data." (PMID 34638692, 2021). "For example, considering patients affected by both ‘Rod-cone dystrophy’ (HP:0000510) and ‘Hearing impairment’ (HP:0000365), the top two genes predicted are USH2A (HGF: 9.53) and ADGRV1 (HGF: 8.31), both known to cause Usher syndrome that affects both visual and hearing systems." (PMID 32271766, 2020). "This included the adhesion G protein-coupled receptor V1 (ADGRV1) gene which has a role in the development of auditory hair bundles in mice and is related to Usher syndrome, a highly heritable disease which consists of various symptoms including hearing loss and vision impairment." (PMID 29670642, 2018). "Usher syndrome is heterogenous, both in terms of clinical presentation and genetic origin, with a number of diverse genes known to carry pathogenic mutations (Type 1: MYO7A, USH1C, PCDH15, CDH23, USH1G, and CIB2; Type 2: USH2A, ADGRV1, and WHRN; Type 3: CLRN1)." (PMID 38474133, 2024). "Genomic DNA sequencing revealed that the siblings shared two monoallelic variants in two genes linked to Usher Syndrome (USH genes), a recessive disorder of the ear and the retina: a rare pathogenic truncating variant in USH1G and a previously unreported missense variant in ADGRV1." (PMID 37893031, 2023). "In organoids generated from patients with RP, a mislocalisation of Usherin, and its interacting partner ADGRV1 were observed; however, both proteins appeared to be entirely absent in Usher syndrome patient-derived organoids." (PMID 38474133, 2024).
epilepsy (26 papers, 2012 to 2026). A brain disorder characterized by episodes of abnormally increased neuronal discharge resulting in transient episodes of sensory or motor neurological dysfunction, or psychic dysfunction. "ADGRV1 variants associated with FSs/epilepsy respond well to antiepileptic drugs, implying a clinical significance." (PMID 37305674, 2023). "This case report highlights the link between the de novo variant of ADGRV1 and the ictal bradycardia/asystole phenotype and implicates the importance of genetic testing in adult epilepsy patients." (PMID 40217298, 2023). "The ADGRV1 gene is an epilepsy-associated gene located at the 5q14.3 chromosomal locus, a site that has been previously reported to be associated with myoclonic epilepsy due to haploinsufficiency." (PMID 40217298, 2023). "Although previous experimental studies suggested that ADGRV1 variants were associated with epilepsy, clinical evidence is limited and the phenotype spectrum is to be defined." (PMID 35813073, 2022). "The genotype-phenotype correlations of the ADGRV1 variants in epilepsy and audio-visual disorders were analyzed." (PMID 35813073, 2022). "A previous study on 48 families with epilepsy with febrile seizures (FSs) identified a nonsense ADGRV1 variant in a family with two affected siblings, which provided initial clinical evidence on the association between ADGRV1 and epilepsy." (PMID 35813073, 2022). "In conclusion, we identified 10 ADGRV1 variants in nine unrelated cases with FS or epilepsy with antecedent FS." (PMID 35813073, 2022). "ADGRV1 variant-associated FS/epilepsy presented favorable responses to antiepileptic drugs, implying a clinical significance." (PMID 35813073, 2022). "We reviewed all reported ADGRV1 variants and analyzed the correlation between genotype and phenotype, aimed to determine the roles of ADGRV1 variants in epilepsy and its relationships with audio-visual abnormalities." (PMID 35813073, 2022). "The incomplete penetrance suggests that ADGRV1 variants caused a relatively lower pathogenicity (susceptibility) to epilepsy, coincident with the relatively mild phenotype of FS-related epilepsy shown in this study." (PMID 35813073, 2022). "ADGRV1 variants associated with FS/epilepsy presented favorable responses to AEDs, implying a clinical significance." (PMID 35813073, 2022). "Contrary to SCN1A variant-associated epilepsy that revealed seizure was aggravated by sodium channel blockers, ADGRV1 variants were associated with mild epilepsy with favorable responses to antiepileptic drugs." (PMID 35813073, 2022). "This study identified ADGRV1 variants in nine unrelated cases with FS-related epilepsy, including two heterozygous frameshift variants, six heterozygous missense variants, and a pair of compound heterozygous missense variants." (PMID 35813073, 2022). "Our data collectively provide first insights into the molecular pathophysiology associated with ADGRV1 defects in the brain, which may relate to the development of epilepsy associated with mutations in ADGRV1." (PMID 42002803, 2026). "Dysfunction or absence of ADGRV1 from primary cilia may underly the pathophysiology of human Usher syndrome type 2 and epilepsy caused by mutations in ADGRV1." (PMID 40103630, 2025). "However, almost nothing is known about the pathomechanisms that lead to epilepsy associated with mutations in ADGRV1." (PMID 40103630, 2025). "Dysfunction or absence of ADGRV1 from primary cilia may underlay the pathophysiology of human USH type 2 and epilepsy caused by mutations in ADGRV1." (PMID 40103630, 2025). "In addition, more recently, mutations in ADGRV1 have been associated with various forms of epilepsy." (PMID 40103630, 2025). "These clues suggested that ADGRV1 variants were potentially associated with epilepsy." (PMID 35813073, 2022). "Previous studies suggested a potential association between ADGRV1 gene and epilepsy." (PMID 35813073, 2022).